CCR2 (C-C motif chemokine receptor 2)
Diseases named in the same sentence as CCR2 in open-access papers (continued):
Sharing a sentence is not in itself a finding about the gene and the disease.
tumor (continued). "Importantly, mRNA levels of Ccr2 and Ccr5, known to be differentially expressed by TAM1 and MDSCs, were enhanced in isolated control tumours compared to liver tissues, postulating an enhanced presence of Ccl2 and Ccl5-responding myeloid cells." (PMID 34830835, 2021). "Several preclinical studies have demonstrated that CAR T cells expressing chemokine receptors, including C-X-C motif chemokine receptor 1 (CXCR1), CXCR2, CCR2, CCR4, and C-C chemokine receptor type 2 (CCR2b), showed enhanced trafficking to tumor lesions and superior antitumor efficacy." (PMID 34209505, 2021). "Representative images from the HPA database also showed that the staining intensity of CCR2 was strong in normal tissue but not detected in tumor." (PMID 34251980, 2021). "Expression of CCR2 and CCL2 by human tumor lines and patient samples." (PMID 34804061, 2021). "Indeed, these studies suggest that the major monocyte recruiting pathways (M-CSF/CSF-1R, CCL2/CCR2, CCL3/CCR1, CCL3/CCR5, CCL5/CCR5 and CX3CL1/CX3CR1) enable tumor survival by supplying the TME with pro-tumorigenic TAMs." (PMID 34988021, 2021). "Thus, together with direct effects on tumor cells, targeting the CCL2/CCR2 axis likely generates multiple attacks on multiple unfavorable cell types (including cancer cells) within the TME." (PMID 34804061, 2021). "Overall, tumor microenvironment contains many factors favoring the development of M2 like TAMs, CCL2/CCR2 signaling axis not only play a major role in recruitment of monocytes/MØs to contribute to functional polarization of MØs but also can directly polarize MØs." (PMID 34804061, 2021). "In mice injected subcutaneously with a tumor cell line, tumoral accumulation of Tregs but not conventional CD4+ CD25-Foxp3- T cells was significantly reduced by CCR2 deficiency." (PMID 34804061, 2021). "Preclinical evidence showed that tumor and stroma cells release C–C motif chemokine ligand 2 (CCL2) to recruit monocytes expressing C-C chemokine receptor type 2 (CCR2); these recruited CCR2-expressing monocytes will finally polarize into TAMs, contributing to tumor cell survival." (PMID 33916915, 2021). "CCX872, a small molecule antagonist of CCR2, can impede MDSC invasion into tumour sites." (PMID 34464477, 2021). "Even if the CCR2 axis is dominantly involved in TAM and MDSC recruitment at tumor sites, it also contributes to Treg recruitment in the TME, although, in human tumors, the expression of CCR2 on T cells does not appear selective for TA-Tregs, at least in NSCLC and CRC." (PMID 33924428, 2021). "Thus, the CCL2/CCR2 axis not only regulates MPP production and therefore tumor invasion/metastasis via its action on TAMs, but also via its action on tumor cells directly." (PMID 34804061, 2021). "Albeit not investigated in neuroblastoma, studies in solid tumors show that the axis can be disrupted either by inhibiting CCR2 or via anti-CCL2 antibodies, thereby preventing the recruitment of suppressive myeloid cells and initiation of their tumor-promoting effects." (PMID 33917501, 2021). "Also, the expression of CCR2 and P2RY13 in LUAD tumor and normal tissues was verified by the THPA database." (PMID 34494914, 2021). "CCR2 expressing monocytes are driving tumor progression, and therefore, inhibiting the CCL2-CCR2 axis could stop tumor expansion." (PMID 33918295, 2021). "The expression of CCR2 and P2RY13 was reduced in tumor tissues (P < 0.05)." (PMID 34494914, 2021). "Apart from cell homing, CCR2+ Tregs had a heightened ability to produce IL-10 and self-renew than CCR2-/- counterparts, and also expressed higher levels of CD39 but not CD73 when tumor Tregs were separated into two cohorts according to their CCR2 expression." (PMID 34804061, 2021). "We did not observe significant improvement in tumor growth or survival in DT-treated FoxP3DTRCcr2–/– mice beyond that seen in Ccr2–/– mice or FoxP3DTR mice treated with DT." (PMID 33976133, 2021).
tumor (continued). "The preferential tumor recruitment of Tregs was intrinsic to Tregs since parabiosis experiments between WT and Foxp3-EGFP CCR2-/- mice show that EGFP+ CCR2-/- Tregs which migrated to the tumor tissue represented only 20% of total Treg in both WT hosts and CCR2-/- hosts." (PMID 34804061, 2021). "Similarly, a combination therapy, comprising PF‐04136309, a CCR2 inhibitor with FOLFIRINOX, achieved generated effective tumor response and achieved local tumor control in 97% of patients with pancreatic cancer." (PMID 32508035, 2020). "Collectively, these data showed that we could use a commercially available CCR2 antagonist to assess the effects of CCR2 inhibition on MDSC recruitment and syngeneic tumor cell growth in WT mice." (PMID 33322474, 2020). "By binding CCR-2, CCL-2 promotes tumor growth and metastasis." (PMID 33228048, 2020). "Similarly, mouse models of Lewis lung carcinoma demonstrated that TAMs were derived from CCR2 driven recruitment of Ly6Chi monocytes and blockage of CCL2 decreased tumor growth." (PMID 32038499, 2020). "To further clarify the mechanism underlying the functions of the four previously discovered key genes (CCR2, CCR4, P2RY12, and P2RY13) in the tumor microenvironment, we divided LUAD patients into high-expression groups and low-expression groups according to the four gene expression levels." (PMID 33318300, 2020). "Gem alone could increase the number of TAMs in PDAC lesions, and CCR2 and/or CSF1R inhibitors could reverse this increase and dramatically reduce tumour masses." (PMID 32061257, 2020). "Similarly, the co-expression of CCR2 and CCR4 in CAR T cells has been shown to improve homing to the tumor site and anti-tumor function in mouse models of malignant pleural mesotheliomas, Hodgkin’s lymphoma and neuroblastoma, respectively." (PMID 32570906, 2020). "A lack of CCR2 expression on HSPCs reduces splenic myelopoiesis, impairs the suppression activity of tumor MDSCs, allows an increase in the number of tumor-infiltrating IFNγ+CD3+CD8+ CTLs, and enhances immunotherapy efficacy." (PMID 32582203, 2020). "While there was a slight increase in circulating CCR2+ neutrophils in tumor-bearing animals, there was no increase in CCR2+ neutrophils in the liver." (PMID 32391790, 2020). "Since human CCL2 could bind to murine CCR2 44, we speculate MiV may harness CCL2/CCR2 chemokine axis to track tumor cells, which is similar to donor cells." (PMID 32550891, 2020). "CCR2+ cells were sparsely scattered within the surrounding brain parenchyma in tumor mice, whereas none were ever observed in sham controls." (PMID 32391790, 2020). "Additionally, targeting signalling of CCL2/CCR2 with a CCR2 antagonist was found to remarkably reduce TAM recruitment and polarization, thus enhancing the immunotherapeutic effect of tumour." (PMID 32910558, 2020). "Here, we show that suppression of the CCL2/CCR2 and CXCL10/CXCR3 axes by celecoxib in the tumor and the tumor microenvironment might contribute to antitumor effects." (PMID 32943658, 2020). "In summary, tumor cells are the prime source of MCP-1 that promotes MDSC recruitment, and our genetic and pharmacologic data demonstrate that CCR2 targeting may be an important component of cancer immunotherapy." (PMID 33322474, 2020). "CCL2 synthesis by tumor cells, stromal and bone marrow osteoblasts, subsequently mediate tumorigenesis, metastasis and recruitment of inflammatory monocytes that express CCL2 receptor CCR2 to the tumor sites." (PMID 33062602, 2020). "Additionally, chemokine signaling events such as CCL2/CCR2 signaling and CXCL11/CXCR7 signaling have been reported to play critical roles in tumor angiogenesis." (PMID 33099574, 2020). "Use of CCR2 knockout mice or a CCR2 inhibitor to prevent recruitment of Ly6Chi monocytes did not affect tumor growth." (PMID 32038499, 2020).
tumor (continued). "Because CCR2 is required for guiding MDSC-precursors (and monocytes-macrophages) to their target tissues, systemic application of CCR2 siRNA nanoparticles reduced the number of MDSCs in the TME and decreased the tumor volume as monotherapy." (PMID 32942725, 2020). "CCR2 expression was detected on monocytic myeloid cells including CD14 monocytes and its myeloid precursors, whereas its specific ligand CCL2 (MCP1) is produced by tumor and stromal cells." (PMID 31811337, 2020). "Tumor and stroma cells secrete CCL2 to recruit inflammatory monocytes and TAMs expressing CCR2." (PMID 32471499, 2020). "Because tumour development is largely orchestrated by inflammation, MSCs exhibit upregulation of various chemokine receptors (CCR1, CXCR5 and CCR2) and adhesion molecules (ALCAM, P-selectin and integrins) to facilitate extensive tropism towards specific tumour sites." (PMID 31908585, 2019). "EPC express CCR2, migrate to CCL2 and contribute to tumor neovascularization." (PMID 30800123, 2019). "CCL-2 released by tumor cells, macrophages, and stromal cells within the TME recruits monocytes that express the receptor CCR-2 and granulocytes (i.e. myeloid-derived suppressor cells; MDSCs) that express the receptor CCR-5 to tumors, thereby driving tumor progression." (PMID 31805946, 2019). "In human pancreatic tumor as well as murine pancreatic lesion model, the tumor microenvironment releases CCL2 and thereby actively recruits CCR2-expressing CD14+CD16− classical monocytes from bone marrow to blood stream, which is a prognostic factor of worse outcome." (PMID 31474975, 2019). "Treatment with poly A:U significantly increased the percentage of M0, M2-like, and Ly6C+CCR2+MHCIIneg cells expressing PD-L1, supporting the hypothesis that combining poly A:U with anti PD1/PDL1 inhibitors could potentiate anti-tumor immunity." (PMID 30949170, 2019). "The same group found that while CCR2 was not necessary for MDSC activation, knockdown of CCR2 resulted in a 50% reduction in tumor-infiltrating MDSCs." (PMID 31396227, 2019). "It has been noted that in EOC, specifically, there appears to be inhibition of MDSCs recruitment to a tumor microenvironment lacking chemokine receptor CCR2." (PMID 31354741, 2019). "We focus on ACKR1 (DARC), ACKR3 (CXCR7), CXCR4, and CCR2, as these are the best studied chemokine receptors in TEC; and suggest that targeting these receptors on the tumor vasculature may prove efficacious in slowing or reversing tumor growth." (PMID 30800123, 2019). "We found that tumours injected in Ccr2RFP/RFP mice had decreased apoptosis (TUNEL+, 2.4 ± 0.2% vs. 3 ± 0.2%, mean ± S.E.M., N = 13–14) and increased proliferation (phospho-histone H3+, 377 ± 15 vs. 316 ± 12 cell mm−2) compared to Ccr2+/+ mice." (PMID 31160587, 2019). "Despite the presence of a minor TA-MAC population in CCR2 knockout mice, we found no significant tumor cell phagocytosis of TA-MAC." (PMID 30602457, 2019). "As expected in the Ccr2 knockout mice we observed a delay in tumor-induced morbidity presumably due to the lack of tumor supporting macrophages." (PMID 30602457, 2019). "Preventing recruitment of macrophages to the tumor site has been achieved through targeting macrophage chemoattractants such as CSF-1 and CCL2 or their corresponding receptors: CSF-1 receptor (CSF-1R) and C-C chemokine receptor type 2 (CCR2)." (PMID 30356656, 2018). "For example, our data show that unlike other models, CCR2-dependent macrophage accumulation at sites of metastatic cell extravasation is not essential for tumor development in the B16F10 model." (PMID 30158126, 2018). "Similarly, CCR2b, the chemokine receptor for CCL2, has been co-expressed on CAR T-cells to exploit the CCR2/CCL2 axis, which facilitates myeloid cell recruitment into the tumor." (PMID 29872437, 2018).
tumor (continued). "To determine if CCR2+HSCs are the subset of cells responsible for the observed efficacy of the combinatorial therapy, we compared the therapeutic effect of bulk HSC + PD-1 vs. CCR2+HSC + PD-1 in tumor-bearing mice." (PMID 30333482, 2018). "The relative amount of YFP+CD3+ cells in tumor was also significantly decreased in the group that received CCR2+MHC-I−/− HSC + PD-1 (mean YFP+CD3+ cells = 0.597% ± 0.2487, n = 5) relative to the group that received CCR2+HSC + PD-1 (p = < 0.0001)." (PMID 30333482, 2018). "T-cells secreted equal amounts of IFNγ when used as effectors against either the tumor-RNA-pulsed dendritic cells derived from CCR2+HSCs, or KR158B tumor cells themselves (p = 0.5176), demonstrating that CCR2+HSCs-derived cells have the capacity to present antigen on their MHC." (PMID 30333482, 2018). "Thus, in comparison with WT KLRG1+ NK cells, KLRG1+ NK cells from Ackr2−/− mice increase tumor killing through enhanced CCR2 responsiveness and resulting recruitment in closer proximity to CCL2-expressing tumor deposits." (PMID 30158126, 2018). "Because recruitment of TAMs to target vessels to induce vascular permeability requires CCL2 and colony-stimulating factor 1 (CSF1) synthesized by tumor cells to target receptor CCR2 and CSF1R on TAMs, inhibition of CCR2 or CSF1R signaling reduces tumor growth and metastasis." (PMID 28467800, 2017). "This ruled out the possibility that a stronger anti-tumor effect of IR in CCR2−/− mice was due to poor tumor vasculature." (PMID 29170400, 2017). "Furthermore, Tumor Necrosis Factor Alfa (TNF-α) activates MSCs to secrete chemokine (C-C motif) ligand 5 (CCL5), C-C chemokine receptor type 2 (CCR2), and the interleukin 8 receptor, beta (CXCR2) ligands that in turn recruit CXCR2+ neutrophils into the tumor." (PMID 28473858, 2017). "Depletion of CCR2+MDSC cells enhanced the therapeutic effect of radiation and a STING agonist, as well as combined radiation plus STING agonist therapy, by decreasing suppression of T cells in the tumor microenvironment." (PMID 29170400, 2017). "Our results showed that l-CDL could downregulate tumor compression-induced CCL2 and CCR2 protein and mRNA expression in spinal cord showing that l-CDL could decline mechanical allodynia as well as microglial activation." (PMID 28587280, 2017). "Our study establishes tumor cell-expressed TRAIL-R as a trigger for cancer cells to secrete CCL2, which, in turn, drives accumulation of a pro-tumorigenic immune microenvironment via host cell-expressed CCR2." (PMID 28212753, 2017). "However, these processes are only consecutive to tumor-mediated immune reprogramming and activation in distant tissue and therefore dependent on CCL2/CCR2 driven S100A8/A9 release." (PMID 28744322, 2017). "Additionally, tumor-derived angiogenesis induced by co-treatment of ganglioside GM1 and macrophages was reduced by the addition of the CCR2 antagonist RS102895." (PMID 28587280, 2017). "This strategy translated into improved homing (>10 fold) to CCL2-secreting neuroblastoma compared to CCR2-negative T cells, as well as greater in vivo anti-tumor activity." (PMID 28331613, 2017). "The tumorigenic features of CCL2/CCR2 signaling were described, but CCL2/CCR2 signaling also plays a protective role in antitumor effects, such as through the recruitment of type 1 cytotoxic gammadelta T lymphocytes to the tumor microenvironment." (PMID 28424406, 2017). "In some tumor models, M-MDSCs express higher levels of F4/80, CD115, 7/4, and CCR2." (PMID 29170400, 2017). "Indeed, tumor-produced nitrosylated CCL2, which is the main ligand for CCR2, has been shown to selectively recruit myeloid-derived suppressor cells (MDSCs) while abrogating recruitment of Th1 and cytotoxic T lymphocytes." (PMID 29020986, 2017). "Of interest, we found that the corresponding receptors of SDF-1α and CCL2, CXCR4 and CCR2 were up-regulated in the THP1 cells, which might amplify the chemotaxis of monocytes into the tumor sites." (PMID 27888616, 2016).
tumor (continued). "Both of these effects, increased basal EPC numbers and tumor-induced increases in EPCs, appeared to be the result of mobilization since Ccr2 deletion did not alter bone marrow EPCs." (PMID 27820834, 2016). "This work demonstrates that although the chemokine crosstalk in the tumor microenvironment (TME) is a complex and overall poorly understood process, both the CCL2:CCR2 and CCL5:CCR5 ligand/receptor pairs have been identified as likely therapeutic targets across several types of cancers." (PMID 27852031, 2016). "More recently study revealed that, mesenchymal stem-like cells(MSLCs), the progenitor cells of fibroblast and adipocyte, which could migrate to tumor sites and then promote tumor growth, were also recruited by CCL2/CCR2 pathway." (PMID 26992207, 2016). "Tumor production of certain chemokines, especially the chemokine CCL2, is a major driver of monocyte mobilization of inflammatory (CCR2+) monocytes from the bone marrow and recruitment into tissues, where the monocytes mature into tumor macrophages, which support the growth of tumor metastases." (PMID 29061951, 2015). "In our study, CCL2 orchestrates CCR2-expressing immunomodulatory cells including Tregs, MDSCs and TAMs in the tumor microenvironment, and generates DCregs partly in collaboration with LCN2 that is released from the CCL2-stimulated tumor cells." (PMID 25883937, 2015). "No significant decreases in tumor number, tumor burden, or alveolar macrophage numbers were detected in CCR2−/− mice at any time point (data not shown)." (PMID 25505466, 2014). "MSCs may be recruited into the tumor through FPR2, CCR2, CXCR1, CXCR2, CXCR4, CXCR6, and CX3CR1 depending on the types and locations." (PMID 25110692, 2014). "Surprisingly, the nitrated/nitrosylated CCL2 does not lose the ability to recruit MDSCs to the tumor, likely due to higher expression of CCR2 in myeloid than in T cells." (PMID 24605112, 2014). "Thus, although all three MCP's bind CCR2 and induce monocyte migration in vitro, MCP-1 is the responsible CCR2 ligand in vivo, in particular, in tumor metastasis." (PMID 23527025, 2013). "Treatment of 6–12 week old Tg-Braf/Ccr2-DTR mice with DT for 10 days resulted in thyroid with a predominant follicular architecture consisting of colloid-containing follicles, with fewer tall cells and PDTC tumor nests." (PMID 23372702, 2013). "CCR2 is expressed on two different types of none-malignant cells at the tumor site: the endothelium, and the TAMs." (PMID 22279523, 2012). "Furthermore, CCR2 expression by thymic Sirpα+ cDCs and abundant expression of its ligands, particularly, CCL2 by tumor-bearing mice prompted us to examine the function of thymic Sirpα+ cDCs in tumor-bearing mice." (PMID 22815949, 2012). "We finally proved that the negative selection rather than Treg differentiation ensued in a CCR2-dependent manner once the tumor-specific antigen was secreted into bloodstream." (PMID 22815949, 2012). "CCR2 expression by Sirpα+ cDCs prompted us to examine the function of Sirpα+ cDCs in tumor-bearing mice, because CCR2 ligands, particularly CCL2, are abundantly expressed in tumor-bearing mice." (PMID 22815949, 2012). "We further show that the administration of CCR2-Ig, that selectively and specifically neutralize CCL2, to mice in which CCR2 is expressed only on tumor cells, further suppressed tumor development, implicating for the key role of this chemokine supporting tumor survival in an autocrine manner." (PMID 22279523, 2012). "Although CTL007 has several chemokine receptors matching chemokine produced by CRC cells, predominant expression of CCR2 (65%) by the T cells and the relatively higher amount of CCL2 secretion by tumor cells may have been a decisive factor in T-cell migration." (PMID 21450101, 2011). "Our study demonstrates the role of CCR2 and CCL2 in migration of CTLs towards tumor." (PMID 21450101, 2011).